LINC01052 (long independently transcribed non-coding RNA 1052)
Gene: Long non-coding RNA gene on chromosome 13 (65,866,053 to 65,965,825, forward strand). Ensembl gene ENSG00000234767.
Diseases named in the same sentence as LINC01052 in open-access papers:
LINC01052 is named in the same sentence as 1 disease in open-access papers, as found by Europe PMC text mining. Sharing a sentence is not in itself a finding about the gene and the disease.
LINC01052 shares sentences with these, for which no sentence is quoted: schizophrenia (1 paper).